ALK (ALK receptor tyrosine kinase)
Diseases named in the same sentence as ALK in open-access papers (continued):
Sharing a sentence is not in itself a finding about the gene and the disease.
lung cancer (continued). "Rearrangements in the anaplastic lymphoma kinase (ALK) gene occur in 3–7% of patients with non-small cell lung cancer (NSCLC), and ALK-positive lung cancer has been defined as a distinct clinical and molecular subtype of NSCLC." (PMID 31154543, 2019). "Especially, three anti-lung cancer drugs target genes (DHFR, GART and ALK) also presented in the DEGs." (PMID 30642283, 2019). "Similar to ALK and ROS1 fusion-positive lung cancers, TRK fusion-positive cancers can develop off-target resistance to tyrosine kinase inhibitor therapy." (PMID 31738426, 2019). "Lung cancer was the most commonly reported neoplasm, and EGFR, KRAS, and ALK analysis using polymerase chain reaction or fluorescence in situ hybridization was achieved in 67%–100% of the specimens." (PMID 31179853, 2019). "Recently, however, TK fusions have been identified involving ALK, ROS1 and RET kinases in 3–7, 1–2, and 0.7–2% of lung cancer, respectively." (PMID 29455670, 2018). "This review concentrates on various lung cancer biomarkers, including EGFR, ALK, and BRAF, as well as their potential mechanisms of drug resistance." (PMID 29973561, 2018). "PCR amplification, using primers located in the kinase domain of ALK, confirmed the presence of ALK in our resistant cells and in EML4-ALK positive lung cancer cells, which served as a positive control." (PMID 30290811, 2018). "This study demonstrated that the neuregulin-1 and P2Y purinergic G-protein coupled receptor proteins mediate resistance to the ALK inhibitors, TAE684 and crizotinib, in lung cancer." (PMID 29973561, 2018). "Our study also highlights that these 70 HKGs maintain low levels of variance across tumour samples when compared to accepted markers of lung cancer (e.g., KRAS, ALK, RET)." (PMID 29761043, 2018). "Lorlatinib has been reported to be effective in lung cancer patients with brain metastasis, with an ORR in target lesions reaching 60% in ALK/ROS1 translocated tumors." (PMID 29435193, 2018). "MET is considered a strong candidate given its response to crizotinib, currently a treatment for ALK- and ROS1-rearranged lung cancers, however, MET alterations are uncommon, occurring in approximately 5% of NSCLC." (PMID 29914100, 2018). "The second-generation anaplastic lymphoma kinase (ALK) tyrosine kinase inhibitors (TKIs) alectinib and ceritinib are standard treatment options for patients with non–small cell lung cancer (NSCLC) positive for ALK fusion genes." (PMID 29796191, 2018). "In the multivariable analysis, only lung cancer as well as the presence of ARID1A, KRAS, ALK, and MYC alterations and liver metastasis remained significant predictors of a poorer survival (all P < 0.50)." (PMID 29866143, 2018). "We were particularly interested in the intron 19 region (I19) of ALK, since portions of I19 have been found in the mRNA transcripts of two ALK fusion genes, EML4-ALK and PPFIBP1-ALK, detectable in lung cancer and myofibroblastoma, respectively." (PMID 29535836, 2018). "Recently, the second-generation ALK inhibitors ceritinib and alectinib have shown promising clinical activity in ALK-positive lung cancer and have received FDA approval for the treatment of crizotinib-refractory, ALK-rearranged lung cancer." (PMID 28938595, 2017). "To prospectively identify mechanisms of resistance to EGFR, ALK, BRAF, and MEK inhibition in lung cancer, we performed CRISPR-Cas9 drug resistance screens in five cancer cell lines with different alterations in the RTK/Ras/MAPK pathway." (PMID 28145866, 2017). "In this paper we utilized three transcriptome-based platforms and compared results with the gold standard of FISH testing for the detection of ALK, ROS1 and RET fusions in lung cancer." (PMID 28181564, 2017). "ALK, ROS1 and RET gene fusions are important predictive biomarkers for tyrosine kinase inhibitors in lung cancer." (PMID 28181564, 2017).
lung cancer (continued). "Fortunately, over past decades, the finding of some driver genes in NSCLC, such as epidermal growth factor receptor (EGFR), anaplastic lymphoma kinase (ALK) and kirsten rat sarcoma viral oncogene homolog (KRAS), was a major breakthrough in lung cancer field." (PMID 28423587, 2017). "Loss of KEAP1, a negative regulator of NFE2L2/NRF2, modulated the response to BRAF, MEK, EGFR, and ALK inhibition in BRAF-, NRAS-, KRAS-, EGFR-, and ALK-mutant lung cancer cells." (PMID 28145866, 2017). "According to data derived from studies of lung cancer, EML4-ALK fusion occurs through a paracentric inversion within the short arm of chromosome 2, where EML4 and ALK genes are both located." (PMID 28535796, 2017). "In lung cancer, primary resistance to EGFR- or ALK-targeted tyrosine kinase inhibitors is a result of genetic alterations in or outside of the primary target." (PMID 28685150, 2017). "In addition, post-transcriptional and post-translational modifications of ALK may have also occurred in certain cell types, since discrepant results between ALK transcript and protein expression have also been demonstrated in some melanoma and lung cancer cell lines." (PMID 28837676, 2017). "The Archer® FusionPlex®ALK, RET, ROS1 v2 allowed the expected detection of the fusion breakpoints present in the samples: EML4-ALK (E6:A20) and CCDC6-RET (C1:R12) for the commercialized sample, and EML4-ALK (E6:A20) for the human lung cancer cell line H2228." (PMID 28970558, 2017). "In the same study, crizotinib (Pfizer), an ALK, MET and ROS1 inhibitor, was used to generate resistant lung cancer cell lines." (PMID 27486382, 2016). "It appears that some types of oncogenes regulate lung cancer progression or suppression, such as EGFR or ALK." (PMID 27542716, 2016). "IASLC recommends ALK testing in patients with Stage IV lung cancer and encourages it in patients with Stage I, II or III lung cancer." (PMID 26838801, 2016). "ALK TKI was switched to radio-chemotherapy, which was well tolerated and led to reduction of the primary lung cancer." (PMID 26968843, 2016). "Targeting oncogenic drivers, such as epidermal growth factor receptor (EGFR) and anaplastic lymphoma kinase (ALK), has brought the most encouraging improvements in lung cancer treatment." (PMID 26919104, 2016). "The ALK inhibitor Crizotinib has shown therapeutic effects in the GL261 model and is currently in clinical trials for patients with lung cancer." (PMID 27579614, 2016). "Nevertheless, we confirmed that ALK-positive lung adenocarcinoma is typically solid, aggressive, and more likely to involve the local lymphatic system, compared to EGFR-positive lung cancer." (PMID 27518729, 2016). "In patients with ALK-positive ALCL, there are efforts to study the use of crizotinib, an oral small-molecule tyrosine kinase inhibitor of ALK, which has been FDA approved for the treatment of lung cancer harboring a translocation in the ALK gene." (PMID 27071634, 2016). "Rearrangements in the anaplastic lymphoma kinase (ALK) gene, occurring in 2-7% of NSCLC, also define a distinct molecular subtype of lung cancer." (PMID 26544515, 2016). "Similar findings were also reported in ALK-positive anaplastic large cell lymphoma (ALK+ALCL), gastric cancer, lung cancer, HCC, breast cancer, endometrial cancer and esophageal squamous cell carcinoma." (PMID 26317546, 2015). "Our panel included 22 genes, although the approved predictive biomarkers in colon and lung cancer are quite few (KRAS, NRAS, EGFR, ALK)." (PMID 25637035, 2015). "At the molecular level, all lung carcinomas showing diffuse overexpression of p16Ink4A and harboring genetic alterations involving EGFR and ALK had an excellent outcome, as represented in S2 Table." (PMID 26674347, 2015). "For example, MyD88/TRAF6 and MEK/ERK pathways enhance PD-L1 expression in multiple myeloma, while constitutive activation of anaplastic lymphoma kinase (ALK) drives PD-L1 expression in certain lymphomas and lung carcinomas." (PMID 26217588, 2015).
lung cancer (continued). "In the case of ALK-positive cancers, as well as EGFR-mutant lung cancer, resistance develops on average within the first 2 years of therapy." (PMID 24842630, 2014). "For lung cancer, factors, such as age, gender, stage, smoking history, Myc protein level, and EGFR/KRAS/ALK alteration status were included in the multivariate model." (PMID 25333947, 2014). "Of note, in lung cancer, a positive ALK FISH test and ALK IHC have been proposed as screening tools to detect ALK alterations being considered sufficiently sensitive to indicate treatment with crizotinib." (PMID 25083769, 2014). "Patients with ALK-positive lung cancer comprise only 4-5% of those with NSCLC; however, lung cancer is a highly prevalent disease, and therefore ALK-driven tumors represent a relatively large target population when compared to rare tumors." (PMID 25277503, 2014). "Crizotinib, developed for ALK- positive lung cancer, also inhibits ROS1 and is in a clinical trial for ROS1- positive lung cancer." (PMID 24386191, 2013). "In our case, the tumor is characterized by the typical molecular profile of lung carcinomas arising in smokers, with EGFR and ALK wild type phenotype." (PMID 23844609, 2013). "In lung cancer, the well-developed epidermal growth factor receptor (EGFR) and the newly emerging EML4-anaplastic lymphoma kinase (ALK) are important therapeutic targets." (PMID 23109866, 2012). "A great deal of progress has been made in the target therapy for nonsmall cell lung cancer (NSCLC), largely owing to the development of small-molecular inhibitors, such as epidermal growth factor receptor (EGFR) and ALK." (PMID 23342255, 2012). "The first to be discovered were in prostate cancer, where about half of all cases have the TMPRSS2-ERG fusion gene, and lung cancer, where around 5% of lung cancers have a fusion that activates the ALK tyrosine kinase, the EML4-ALK fusion." (PMID 23260012, 2012). "An inversion event on the short arm of chromosome 2, resulting in the fusion of ALK gene with the EML4 gene locus, is the most common aberration of the ALK gene in lung cancer." (PMID 22825000, 2012). "Mass spectrometry (MS) coupled with anti-phosphotyrosine antibodies identified different patterns of tyrosine kinase signaling in lung cancer cells and tumors, and this approach was able to identify cells driven by oncogenic EGFR, PDGFR, and ALK." (PMID 20976048, 2010). "By integrating structural bioinformatics with molecular and expression data, this study aims to reinforce the role of EGFR, ALK, KRAS, and PD-1 as precision targets in lung cancer, providing a foundation for future diagnostics, therapeutic design, and personalized oncology strategies." (PMID 40927719, 2025). "Overall, patients with non-pulmonary malignancies harboring ALK alterations exhibited shorter PFS on targeted therapy than those with ALK-positive lung cancer." (PMID 41246301, 2025). "Still, FISH versus NGS testing for ALK rearrangements is an ongoing area of debate, as the type of rearrangement may affect the accuracy of FISH in lung cancers, for example." (PMID 40161372, 2025). "Crizotinib and lorlatinib have been used in ALK-positive lung cancer and have shown efficacy in ALK-positive IMT at other sites, whereas ALK fusion-negative patients do not respond to these drugs." (PMID 40636700, 2025). "Known lung cancer genes (EGFR, KRAS G12C, ALK, MET, RET) were found in 33 patients; 11 had genes relevant to both lung and other cancers (ERBB2, BRAF V600, NTRK), and 37 had genes typically linked to other malignancies (NF1, PIK3CA, PALB2, FGFR2B, FBX7, RAD51)." (PMID 40244261, 2025). "Among patients with lung cancer, non-smokers are more likely to have genomic alterations such as EGFR variants or ALK gene rearrangements, and these patients have improved survival when treated with tyrosine kinase inhibitors, compared with chemotherapy." (PMID 41114991, 2025).
lung cancer (continued). "As evidenced by recent publication, a 35-year-old man with stable cystic fibrosis, not on CFTR modulators, was found to have ALK-translocated lung cancer after presenting with an assumed bacterial exacerbation." (PMID 40563468, 2025). "It is important to note, however, that first-line immunotherapy is not recommended for patient groups with genomic-driven lung cancers, such as those with EGFR mutations or ALK-positive NSCLC." (PMID 40075700, 2025). "In conclusion, the present meta-analysis demonstrated the feasibility and utility of ctDNA in detecting ALK rearrangements for lung cancer patients, particularly for whom matched tissue is not available." (PMID 40853979, 2025). "In lung cancer, where actionable alterations such as EGFR, ALK, ROS1, and MET have direct therapeutic implications, optimizing patient selection for NGS testing could further enhance cost-efficiency." (PMID 41301039, 2025). "In lung cancer, KIF3A was identified as a fusion partner of ALK in a LUAD patient." (PMID 40002279, 2025). "In a report of two cases of concurrent CLL/SLL and lung cancer, exploring the common genetic association, both CLL had Trisomy 12, and both lung tumors had high PD‐L1 expression and negative ALK mutation." (PMID 41476748, 2025). "Five ALK tyrosine kinase inhibitors (TKIs) are currently approved by the U.S. Food and Drug Administration (FDA) for the treatment of patients with ALK-positive lung cancer." (PMID 40136367, 2025). "Consistent with what is observed in patients, the implantable models of either EGFR- or ALK-driven lung cancers show no response to anti-PD-1 therapy but show a clear role for adaptive immunity in the response to TKIs." (PMID 40805126, 2025). "In the context of lung cancer, circulating tumor DNA (ctDNA)-based assays enable the identification of clinically targetable mutations, such as EGFR, ALK, and KRAS, without the need for a tissue biopsy." (PMID 41303058, 2025). "Lung cancer patients with ALK and EML4 fusions respond significantly to ALK inhibitors." (PMID 40136367, 2025). "At the molecular level, lung cancers in non-smokers often harbor specific genetic mutations such as those in the EGFR gene, KRAS mutations, and ALK rearrangements." (PMID 40821300, 2025). "ALK, ROS1, RET, and NTRK1 fusions are observed frequently in lung cancer." (PMID 40223139, 2025). "ALK-/ROS1 inhibitors were used in 199 patients, including 180 patients with lung cancer." (PMID 40896464, 2025). "ALK tyrosine kinase inhibitor (TKI) alectinib was effective as adjuvant therapy in patients with non‐small cell lung cancer, but was not confirmed effective in patients with IMT." (PMID 39592917, 2025). "For lung cancer, the miRNAs known and identified by MoPC are miR-7–5p and miR-21–5p (chemosensitive and chemoresistant, respectively) and miR-200c-5p and miR-223–5p with EGFR-TKI and ALK-TKI sensitivity." (PMID 38512819, 2024). "Because CYFRA21‐1 measures fragments of cytokeratin, the different cytokeratin positivity rates may explain the difference in CYFRA21‐1 values in ALK‐ and EGFR‐positive lung cancer." (PMID 38400801, 2024). "The anaplastic lymphoma kinase (ALK) protein is a tyrosine kinase in normal cells, and ALK gene alterations can be potent drivers of oncogenes in a variety of tumor types including lung cancer and lymphoma." (PMID 39205743, 2024). "Next, TF expression was evaluated in ALK-positive NSCLC lung cancer cell lines (H3122 and H2228) and ALK-negative NSCLC lung cancer cell lines (H1299 and A549)." (PMID 37940761, 2024). "In this case, the NRAS mutation was predominantly identified, the most common gene mutations in lung cancer are all negative, including EGFR, KRAS, BRAF, ALK, ROS1, and so on." (PMID 39507527, 2024).
lung cancer (continued). "In this scenario, customized medicine has brought successful outcomes in drug selection for lung cancer patients with NSCLC based on the paradigms of their molecular profiles, specifically those with positive genetic alterations in EGFR, ALK, ROS-1, HER2, BRAF, MET, and RET genes." (PMID 39410578, 2024). "Rearrangements of ALK have been observed in almost 10% of NSCLC patients, prompting researchers to conduct studies using ALK tyrosine kinase inhibitors as a novel treatment for lung cancer." (PMID 39239557, 2024). "Efficacy in a checkpoint inhibitor resistant setting was also seen in patient 20202 with EGFR and ALK negative non–small cell lung cancer (NSCLC) refractory to nivolumab therapy." (PMID 38546220, 2024). "It is worth noting that anaplastic lymphoma cells, unlike lung cancer cells, show very strong ALK expression, and therefore, different antibodies are used in ALCL diagnosis than in NDRP." (PMID 39457620, 2024). "Toceranib phosphate is also capable of blocking PDGFR, VEGFR, Flt-3, CSF1R, RET, ALK, and AXL, which may provide potential benefits for dogs with primary lung cancer." (PMID 39902337, 2024). "Here, we present a 10XGenomics scRNA-seq experiment, providing a controlled heterogeneous environment using lung cancer cell lines characterised by the expression of seven different driver genes (EGFR, ALK, MET, ERBB2, KRAS, BRAF, ROS1), leading to partially overlapping functional pathways." (PMID 38307867, 2024). "The findings of an electronic search for publications using RET-FISH in lung cancer were compared with the results obtained at the Grenoble University Hospital where 784 EGFR-, KRAS-, ALK-, and ROS1-negative NSCLCs were tested by RET break-apart FISH and confirmed by RNA-sequencing (RNA-seq)." (PMID 39507413, 2024). "Anaplastic lymphoma kinase (ALK), epidermal growth factor receptor (EGFR), ROS proto-oncogene 1 (ROS1), and serine/threonine-protein kinase B-Raf (BRAF) inhibitors have become key components of lung cancer therapy." (PMID 38785748, 2024). "In recent years, the prognosis of lung cancer has depended on the presence or absence of EGFR mutation and ALK fusion protein." (PMID 37747688, 2024). "Our cohort was comprised of 20 patients with EGFR-mutant tumors, two patients with ALK-driven tumors, and two patients with non-EGFR and non-ALK mutated lung cancer." (PMID 38806586, 2024). "Based on assay design and coverage of key intronic regions of the genome, we were also able to detect a broad range of clinically relevant fusions, such as EML4::ALK, RET, and ROS1 rearrangements with diverse gene partners in lung carcinomas, BRAF::KIAA1549 and EGFRvIII alterations in gliomas." (PMID 39289779, 2024). "For example, tumor-infiltrating lymphocytes were dramatically reduced in EGFR-mutated lung cancer; whereas CD8 + T cells were either absent or functionally impaired in ALK-positive lung cancer." (PMID 38031067, 2023). "Thus, we conducted a correlation study between FGF11 and EGFR (19DEL, L858R), EGFR (Exon 20ins), KRAS (G12C), ALK, ROS1, BRAF, NTRK1/2/3, MET, and RET, which are all recommended by the NCCN guidelines for the diagnosis of nonsmall cell lung cancer." (PMID 37250453, 2023). "Several oncogenic fusions protein families exist, with ROS proto-oncogene 1 (ROS1), anaplastic lymphoma kinase (ALK), neurotrophic tyrosine receptor kinase (NTRK), and neuregulin 1 (NRG1) being some of the most common partners that are primarily detected in lung cancers." (PMID 37958963, 2023). "Anaplastic lymphoma kinase (ALK) fusion mutation is more common in younger and never-smoking lung cancer patients." (PMID 37007097, 2023). "Our study extended the spectrum of ALK fusion partners in ALK-positive NSCLC, and we reported a new ALK fusion, PPFIA1-ALK and ALK-C2orf91(intergenic), and its sensitivity to alectinib firstly in lung cancer." (PMID 37706178, 2023).